C3 (complement C3)
Diseases named in the same sentence as C3 in open-access papers (continued):
Sharing a sentence is not in itself a finding about the gene and the disease.
viral infection (57 papers, 2012 to 2026). "Significant signals for specific viral infections signals were most commonly reported with C5 inhibitors but showed the strongest statistical association with C3 inhibitors." (PMID 40860872, 2025). "C3 inhibitor use was associated with higher odds of reporting viral infections (ROR = 3.52, 95% CI: 2.54–4.89, P < 0.001)." (PMID 40860872, 2025). "Others have shown that transferred B-cells from WT mice are able to functionally reconstitute C3 deficient mice for protection against viral infection." (PMID 33746963, 2021). "Viral infection induced complement activation (C1q and C3), which may cause the lysis of bystander neurons." (PMID 34408631, 2021). "The protective role of C3 against viral infection is caused by activation of the humoral response." (PMID 33244380, 2020). "Previous experiments have shown viral infections can inhibit C3 complement production, and that the loss of IL1RN can enhance susceptibility to viral infections, which may suggest an interaction between dietary olive oil, the host and the virome." (PMID 30781503, 2019). "Both CD4+ and CD8+ T-cells responses in C3 deficient mice are decreased in viral infection models." (PMID 22973398, 2012). "This reveals the presence of a regulatory loop through which this lncRNA protects against viral infection by promoting complement C3 activity." (PMID 40237496, 2025). "Complement inhibitors, particularly C3 agents, are associated with significant reporting of infectious AEs in FAERS, including specific viral infections like influenza and herpes." (PMID 40860872, 2025). "There exist significant differences in the number of reported viral infection adverse events across cases with different inhibitor groups, with the C5 inhibitor group having markedly more adverse cases than the C3 inhibitor and Factor B inhibitor groups." (PMID 40860872, 2025). "Intriguingly, stratified ROR analysis revealed that C3 inhibitors exhibited significantly higher odds of viral infection reports relative to other classes (C5 and Factor B)." (PMID 40860872, 2025). "Previous clinical studies have shown that bacterial, fungal, or viral infections can lead to early activation of complement component 3 (C3), resulting in depletion of plasma C3 and upregulation of C3 cleavage forms, including C3a and C3b." (PMID 39022312, 2024). "Deposition of complement C3 is reported in the human brain after viral infection, including SARS-CoV-2 and HIV15,60." (PMID 37704739, 2023). "With viral infection alone, in control samples, C3 (P < 0.0021), C5 (P < 0.0001), and C1Inh (P < 0.0008) were significantly increased." (PMID 37534622, 2023). "While complement C3 is critical for inducing a humoral and cell-mediated response to vaccination and viral infection, little published information exists relating to the timing and activity levels of induced complement cascades in cattle." (PMID 36225796, 2022). "In contrast, PEDV nsp1 inhibited CCAAT/enhancer-binding protein β (C/EBP-β) phosphorylation to reduce complement component 3 (C3) expression, which is considered to play a crucial role in preventing viral infection." (PMID 36619958, 2022). "Interfering with C3, or disrupting opsonins that tag synapses, such as C1q or C3b, would likely create significant vulnerability to bacterial or viral infections." (PMID 35600620, 2022). "The results observed in infected C3-/- confirmed that the complement system protects against liver injury after viral infection." (PMID 35573780, 2022). "Antagonizing C5aR led to a decline in TNTs in DC culture as well as in DC/CD4+ T-cell co-cultures accompanied by a reduction in viral infection and local C3 production by DCs." (PMID 35204813, 2022). "The major source of C3 is liver, but extra-hepatic C3 has been shown to play a key role in enhancing the humoral response to peripheral viral infection." (PMID 28301559, 2017).
viral infection (continued). "The human C3 promoter has been extensively analyzed regarding its regulation by inflammatory signal, such as interleukin 1 and 6, and viral infection." (PMID 25617152, 2015). "Intracellular C3 served as an innate immune activation marker during viral infection." (PMID 40929365, 2026). "However, reports on the regulation of C3 by host molecules following viral infection are fairly limited." (PMID 40237496, 2025). "BST2 and C3 play a role in the immune response and acts as a restriction factor against viral infections, reduced expression of which may indicate a compromised immune defense in sun-exposed skin, making it more susceptible to infections and inflammation." (PMID 39540047, 2024). "To validate the positive impact of the CVP diet on the immune response of C. labrosus juveniles, we assessed the head kidney transcription levels of mx, c3, mhcII, and tnfα in response to bacterial infection (A. hydrophila) and poly I:C (mimicking viral infection)." (PMID 37958080, 2023). "We show that the virus infection in C3-/- mice results in increased viral load and 100% mortality, which can be reversed by adoptive transfer of naïve wild-type (WT) splenocytes, purified splenic B cells, or passive transfer of immune sera from WT, but not C3-/- mice." (PMID 28301559, 2017). "Additionally, investigating the role of C3 in other bacterial and viral infections could provide valuable insights into whether similar immune-modulatory effects are observed across diverse pathogens." (PMID 40008883, 2025). "Furthermore, IL-1β and C3 expression is increased in different viral infections of the CNS." (PMID 37191498, 2023). "and stressors such as viral infection may result in a rapid surge in C3 production, freeing the previously substrate-limited AP and resulting in a catastrophic runaway that overwhelms downstream complement regulators (which are in any case poorly expressed in the brain)." (PMID 32098865, 2020). "Unfortunately, we have also found that lack of C3 may cause some immune deficiency in the C3 KO piglets and make them more susceptible to bacterial and viral infections." (PMID 28694465, 2017). "DEGs unique to infected cells mapped to host defense (MYD88, C3, CASP4, JAK2, and OSM), viral infection (RNASE6 and SVVORFs), and protein synthesis (RPL18 and RPS16)." (PMID 38887303, 2024). "Furthermore, viral infection increased the colocalization of presynapses with C1qA, and the decrease in synaptic density was blocked by the KO of C3 and C3aR (the receptor of C3a, the cleavage product of C3), indicating the involvement of complement and subsequent synaptic phagocytosis by microglia." (PMID 34685535, 2021). "Moreover, PEDV nsp1 reduces complement component 3 (C3) expression through inhibiting CCAAT/enhancer-binding protein β (C/EBP-β) phosphorylation via V50, which is crucial in preventing viral infection." (PMID 38793808, 2024). "Neutrophil infiltration was lower in C3-/- than in wt mice at 24 and 48 hrs after MHV-3 infection, indicating that the normal inflammatory response had a protective role against virus infection." (PMID 35573780, 2022). "Even if regulation of complement components, including C3, was reported in trout liver after bacterial challenges, the transcription of the complement component C3 was not affected after viral infection in our studies." (PMID 25338079, 2014). "However, research on the function of C3 and LAMB1 in viral infection is fairly limited." (PMID 40237496, 2025). "C3 could only be used as an antiviral if its IFN stimulatory effects are not adversely affected by the presence of viral infection, in particular the presence of viral antagonists of the IFN pathway." (PMID 23145065, 2012). "Interestingly, except complement C3 (UniProt accession No. I3LTB8) enriched in the complement and coagulation cascades pathway, no other DEPs at 36 hpi were enriched in virus infection-related pathways and innate immune response-related pathways." (PMID 35632606, 2022).
atherosclerosis (53 papers, 2012 to 2025). A disease characterized by the build-up of fatty material and calcium deposition in the arterial wall resulting in partial or complete occlusion of the arterial lumen. "One recent study found that the complement C3 system is involved in the progression of atherosclerosis by vascular remodeling, while another study suggested that complement C3 is associated with a higher future risk of coronary heart disease." (PMID 39409080, 2024). "The finding that complement C3 levels were elevated in PCOS subjects with normal weight is important since increased levels of complement C3 have been associated with increased risk of atherosclerosis." (PMID 37181037, 2023). "Previous studies have shown that complement component 3 (C3) is associated with atherosclerosis and cardiovascular risk factors." (PMID 31829184, 2019). "An association with the pathogenesis of atherosclerosis has been shown for circulating complement C3, and with acute myocardial infarction for titin and fibrillin-1." (PMID 28273075, 2017). "We demonstrated for the first time that the SNP (rs2230500) in PRKCH is associated with CIMT used as a subclinical phenotype for atherosclerosis and complement C3 considered as a signal of the inflammatory process." (PMID 22808203, 2012). "Furthermore, complement factors such as C3 and C4 were found to be linked to the presence of atherosclerosis." (PMID 40612949, 2025). "It is well established that complement C3 is associated with atherosclerosis and CVDs." (PMID 39409080, 2024). "Of these, α-1 antitrypsin has been implicated in atherosclerosis, but in a protective function, and complement C3 products and their cell receptors have been detected by immunohistochemistry in areas with atherosclerotic lesions of different severity in human arteries." (PMID 37293282, 2023). "Indeed, atherosclerosis is often associated also with small vessel disease stroke and animal as well as clinical studies demonstrate that several stages of atherogenesis are regulated by the complement system and in particular C3." (PMID 23977229, 2013). "Recent studies indicate that complement components, notably C3 and C5b-9, accelerate atherosclerosis progression through their interactions with endothelial cells, smooth muscle cells, and immune cells." (PMID 40119227, 2025). "The association between plasma complement C3 levels and coronary heart disease (CHD) within the context of smoking behavior was examined in the CODAM (Cohort on Diabetes and Atherosclerosis Maastricht; sample size n= 562) study." (PMID 40612949, 2025). "C3 activation is particularly crucial in the early stages of atherosclerosis, as it facilitates the clearance of apoptotic cells and debris, thereby reducing the likelihood of necrotic core formation." (PMID 40119227, 2025). "Buono and colleagues reported that disrupted C3 (Complement C3) affects atherosclerosis progression." (PMID 40607379, 2025). "In a murine model of atherosclerosis, CFH deficiency has been shown to limit plaque necrosis in a manner dependent on complement C3." (PMID 39660125, 2024). "Atherosclerosis-specific C3 CD4+ T cells had slightly increased GZMA expression compared to PSA PBMCs and SF." (PMID 38665903, 2023).
atherosclerosis (continued). "For example APOE deficient mice are prone to atherosclerosis, but C3 modulation of lipid metabolism can protect them, while VEGFC is a marker for advanced atherosclerosis and hypercholesterolemia in the same animals." (PMID 27112350, 2016). "We postulate that normal levels of C3 and the presence of properdin appear to be protective in experimental atherosclerosis." (PMID 24667818, 2014). "In the current study, the association between the SNP (rs2230500) in PRKCH and complement C3 was found firstly, and the results showed that the SNP is associated with CIMT that is a subclinical indicator of atherosclerosis." (PMID 22808203, 2012). "Increased C3 deposition within the intima of human atherosclerotic lesions compared with normal vessel intima, in the absence of complement deficiencies or defects, provided support for the suggestion that complement may play a direct functional role in atherosclerosis." (PMID 24278688, 2012). "In chronic vascular inflammation, such as in atherosclerosis or vasculitis, dysregulated C3 signaling in T cells may favor persistent Th1 or Th17 polarization and contribute to vascular immune pathology." (PMID 41187099, 2025). "In summary, C3 in atherosclerosis displays strong cell-type specificity and dual functionality." (PMID 41187099, 2025). "C3 could bind to HDL particles and increased levels of C3 seems to be associated with atherosclerosis." (PMID 36297390, 2022). "Therefore, the present study was conducted to investigate the relationship between circulating C3 complement, lipids and atherosclerotic plaque burden in FH patients with subclinical atherosclerosis." (PMID 34066088, 2021). "Thus, our results strongly suggest that the C3 complement components present in the atherosclerotic ECM are key players in the outside-in signaling that occurs in key vascular cells involved in atherosclerosis progression." (PMID 34066088, 2021). "Increased deposition of C3 within the intima of atherosclerotic lesions suggests that complement may play a direct functional role in atherosclerosis." (PMID 31829184, 2019). "Complement activation is also involved in atherosclerosis, with studies showing elevated deposition of C3 in atherosclerotic lesions as well as presence of C5b-9 and complement regulatory proteins within atherosclerotic plaques suggesting that full complement activation takes place." (PMID 31193778, 2019). "A variety of variables (CRP, complement C3, IL-6 and TNF-α) implicated in the regulation of the inflammatory process and, in turn, in the pathophysiology of arthritides, are relevant in the etiology and the development of atherosclerosis." (PMID 23036698, 2012). "Furthermore, in our previous study, our group found by mass spectrometry and differential proteomics that the ECM of atherosclerotic human aortic arteries is enriched in various active components of the C3 complement system compared to atherosclerosis-free aortic segments." (PMID 40862724, 2025). "Thus, on day 21 of HDBR, the levels of RBP4, APOB and C3 proteins increased, each of which plays an important role in one way or another in modulating the properties of the endothelium and contributing to the development of atherosclerosis, which is a precursor of many cardiovascular diseases." (PMID 38966226, 2024). "Cell-autonomous regulation of complement component C3 by complement factor H (CFH) modulates macrophage efferocytosis and impacts the progression of atherosclerosis." (PMID 39660125, 2024). "In the atherosclerosis dataset GSE28829, CD14 (AUC = 0.938), C1QB (AUC = 0.947), CD53 (AUC = 0.952), LY96 (AUC = 0.904), P2RX7 (AUC = 0.981), C3 (AUC = 0.817), and TNFSF13B (AUC = 0.875) demonstrated favorable diagnostic efficiency for differentiating patients with atherosclerosis from controls." (PMID 37649719, 2023). "Individuals with a history of atherosclerosis showed higher blood concentrations of complement factors C3 and C3a than subjects who have no such a history." (PMID 34573081, 2021).
atherosclerosis (continued). "However, the overall role of complement is complex and the positive regulator of C3 activation, properdin, has not been studied in experimental atherosclerosis." (PMID 24667818, 2014). "Interestingly, C3 levels have been shown to correlate with ABI and the angiographic parameters of atherosclerosis but not with the severity of calcification measured using an arterial calcification score." (PMID 37239465, 2023).